TNF (tumor necrosis factor)
Diseases named in the same sentence as TNF in open-access papers (continued):
Sharing a sentence is not in itself a finding about the gene and the disease.
infection (continued). "Infection reduced the apoptotic population in STS-treated cells in the same manner as observed in TNF/Chx-treated cells." (PMID 21799887, 2011). "In our population, the average time from initiation of anti-TNF therapy to clinical infection was > 15 months, making reactivation a less likely mode of acquisition of disease." (PMID 21605439, 2011). "Many cytokines are involved in VACV clearance in other models of infection and studies in humans including IL-12 and IL-23, TNF-α and IFN-γ." (PMID 21526210, 2011). "This subtype combines increased levels of productive infection with a reduced TNFα response, which correlates nicely with the presence of a GABP instead of an NFκB transcription factor binding site in its LTR." (PMID 21923919, 2011). "The concentration of anti-inflammatory IL-10 was comparable 133 days post-infection but increased in WT mice by day 322 post-infection and remained significantly lower in Tm-TNF mice." (PMID 22132068, 2011). "Others have reported a similar correlation between lipid- and live infection-induced TNF-α expression." (PMID 21931620, 2011). "In contrast, infection with the human apathogenic TCRV was associated with high levels of IL-6, IL-10 and TNF-α." (PMID 21572983, 2011). "The acute phase cytokines, TNF-α and IL-1βand chemokine IL-8 levels increase within 2 h following infection, while IL-6 expressed late, at 8 to 16 h post infection." (PMID 21249123, 2011). "The highest levels of proinflammatory cytokines (IL-6, TNF-α and the murine IL-8 homologue KC) in blood and brain of the infected mice were observed after 6 h of infection." (PMID 21811575, 2011). "The model used entailed aerosol inhalation infection of WT mice, TNF−/− mice and Tm-TNF mice with 100 viable M. tuberculosis H37Rv bacilli." (PMID 22132068, 2011). "At 16 weeks post-infection, unvaccinated animals exhibited a marked up-regulation in the levels of IFNγ and TNFα in comparison to 10 weeks post-infection." (PMID 21533158, 2011). "The expression levels of genes encoding TNF-α, IFN-γ and NOS2 in the lungs of mice treated with TN3-19.12 at 28 days post-infection, were significantly reduced compared to the control IgG1 treated animals." (PMID 21364878, 2011). "The interaction of the two cell types leads to the rapid release of the pro-inflammatory mediators CXCL8 and TNF-α into the microenvironment, thereby potentially maintaining neutrophil influx at the site of infection." (PMID 21589907, 2011). "Regarding the infection of microglial cells with M. tuberculosis and M. bovis, these microorganisms stimulated the production of IL-1A, IL-1B, TNF-α, G-CSF and GM-CSF; besides M. bovis stimulated the production also of IL-6." (PMID 22151930, 2011). "In these studies determination of relative transcription of IL-6, TNF-α, or IL-17 genes was generally used as a measure of the immune response to infection." (PMID 21829346, 2011). "Infection can occur at any time after initiation of anti-TNF therapy, so that a high index of suspicion is required for febrile patients with pulmonary symptoms." (PMID 21605439, 2011). "In contrast, 3h following infection, TNFα and IL-6 transcripts in the lungs of Ncr1gfp/gfp mice were significantly higher compared to the transcripts of these cytokines in Ncr1+/gfp mice." (PMID 21887255, 2011). "It has been confirmed that the Th1 response (IFN-γ and TNF-α) is essential in inhibiting the systemic spread of Salmonella during initial stages of infection." (PMID 21347426, 2011). "Although A/J mice succumb to C. albicans infection early after infection (48 h), they mount a similar Th2-like cytokine storm consisting of high levels of IL-6, IL-10 and TNFα, suggesting a common role for C5 in both pathologies." (PMID 22206032, 2011). "Mice lethally infected with maEBOV (i.p. infection) generated higher TNF-alpha and MCP-1 levels, but lower IFN-gamma and IFN-alpha, compared to non-lethal (s.c.)infection." (PMID 21994766, 2011).
infection (continued). "Untreated WT mice and Tm-TNF mice displayed small compact lesions with tight lymphocytic wedges and a high degree of clear airway spaces at day 33 post infection." (PMID 22132068, 2011). "CD8+ T cell depletion resulted in a drastic reduction of the relative and absolute number of LCMV-specific CD4+ T cells producing IFNγ and TNFα on day 8 and 11 after infection." (PMID 21966366, 2011). "In our study, however, relative to N. meningitidis, TNF-α and IL-8 expression was up-regulated in response to N. lactamica at time points up to 7 hours post infection." (PMID 22028815, 2011). "We postulate that this enhanced inflammation, coupled with increased TNF-α production by alveolar macrophages, ultimately leads to increased systemic dissemination of infection." (PMID 21247482, 2011). "Consistent with chronic lung weight data, Tm-TNF mice displayed significantly increased number of cells in BAL fluid relative to WT mice on day 378 post-infection." (PMID 22132068, 2011). "It should be noted that expression of all of the studied pro-inflammatory cytokines, including TNF-α which presented moderate and stable expression within 30 days, was significantly inhibited by day 60 post-infection with both M. avium strains." (PMID 21738761, 2011). "In contrast, lung inflammation in Tm-TNF mice was similar to WT mice during early infection with similar lung weights at 21, 63 and 133 days post-infection." (PMID 22132068, 2011). "IRAK3, BIRC3 and TNF were dysregulated throughout the entire infection and were classified into the apoptosis pathway." (PMID 21629653, 2011). "The infection of enteric glial cells with M. tuberculosis H37Rv stimulated the production of IL-1A, TNF-α, G-CSF, GM-CSF and, to a lesser extent, of IL-1B." (PMID 22151930, 2011). "Th2 cytokines such as IL-4 and IL-13 are strongly up-regulated during a primary infection while TNFα and IFN-γ remains largely unchanged." (PMID 21414188, 2011). "Local ischemic events occur in response to inflammation and other insults that release TNF-alpha (infection, autoimmune disorders, etc)." (PMID 21914199, 2011). "Infections occurring with biologics (especially TNF inhibitors) often also concern the lower respiratory tract." (PMID 22046967, 2011). "On the other hand, activated T cells recruited to the site of infection help epithelial cells to clear viruses through production of IFNγ and TNF, and induction of epithelial NOS2 expression." (PMID 22022590, 2011). "Anti-TNF agents were discontinued in 14 of 15 patients taking these agents at time of diagnosis of the infection." (PMID 21605439, 2011). "In contrast, the peak of TNF-α production in cell cultures from I-Ab-/- mice occurred with spleen cells from day 7 of infection." (PMID 21814579, 2011). "Controlled release of IL-8, TNF-α play an important role in fighting against infection; however, the uncontrolled release of these cytokines triggers massive influx of neutrophils and granulocytes with subsequent lung injury and dysfunction." (PMID 22110498, 2011). "In contrast, in the infection model, the TNF-α levels were either comparable (at 6 h and 24 h) or significantly lower (at 2 h and 36 h) in WT mice than in plg-/- mice." (PMID 21931850, 2011). "PT also suppressed levels of IL-1β, IL-12, IFN-γ, IL-6, KC, MCP-1 and TNF-α in the airways after PR8 infection." (PMID 21533103, 2011). "Upon initial infection with mycobacteria, macrophages secrete multiple cytokines and chemokines, including interleukin-6 (IL-6), IL-8 and tumor necrosis factor-α (TNF-α), to mediate host immune responses against the pathogen." (PMID 21447195, 2011). "Strong innate and Th1 responses are related to the early stage of infection and protection is believed to be associated with IFN-γ, TNF and NO production." (PMID 21687602, 2011). "The mutant stimulated less cytokine production in the host lungs, especially at 2 and 3 weeks of infection for both TNF-α and IL6 and at 3 and 6 weeks for IL-1β." (PMID 21687631, 2011).
infection (continued). "The Ly6C+Ly6G- population at the site of infection expressed inducible nitric oxide synthase (iNOS) and, when exposed to CpG oligonucleotides, a portion of these Ly6C+Ly6G- cells produced TNF-α." (PMID 22102816, 2011). "Even prior to infection, the ME mucosa was hyperplastic in TNF KO mice, perhaps reflecting reduced apoptosis in the resting ME resulting in the accumulation of excess tissue due to altered homeostatic remodeling." (PMID 21269505, 2011). "Cytokine studies, mainly in a pulmonary model of infection, have confirmed that Th1-biased immune response characterized by IFN-γ, TNF-α and IL-12 production, are linked with asymptomatic and mild forms of PCM." (PMID 21731741, 2011). "In contrast, the infection control group significantly increased TNFα expression 7 days post challenge as well as its secretion 10 days post infection." (PMID 21813005, 2011). "A nearly complete block of apoptosis induced by TNF-α was observed at day 3 post infection (p.i.) illustrated by a reduction in the number of apoptotic cells from ∼60% to ∼10% in infected cells." (PMID 21799887, 2011). "For CD163, IL-10 inducing strains were able to keep the proportions of double positive SLAII/CD163 cells compared to mock-inoculated culture cells while infection with a IL-10-/TNF- strain (3267) produced a clear decline of double positive SLAII/CD163 cells." (PMID 21314968, 2011). "Both STAT1−/− and STAT2−/− mice possessed similar levels of TNF in the serum at 72 hours post-infection, which were 4–5 fold higher than that detected in wild type mice." (PMID 21379341, 2011). "The apparent lack of TH1 immunity during aerosol infection with the outbreak strain M. massiliense CRM-0019 was due to reduced numbers of CD11b+ cells producing TNF-α and IL-12 cells at the site of infection." (PMID 21931831, 2011). "These mediators of inflammation include interleukins such as IL-1, IL-6, IL-8, IL-18 as well as tumour necrosis factor alpha (TNF-α) and others which change the microenvironment and even regulate deleteriously host cellular mechanisms at the site of infection." (PMID 21573018, 2011). "Administration of recombinant TNF-α protected against blood stage infection with Plasmodium chabaudi in mice, while mice deficient for TNF-α controlled P. chabaudi adami blood infections less efficiently." (PMID 21394207, 2011). "The TNFα over-expression during 7.13 infection which was observed in NS-siRNA transfected cells, was abolished in p65-siRNA transfected cells." (PMID 22216156, 2011). "For example, trauma or infection results in the release of proinflammatory cytokines, e.g., interleukin (IL)-6, IL-1, and tumor necrosis factor-α (TNF-α)." (PMID 21352552, 2011). "In sharp contrast, by 21 days post-infection, TNF−/− mice already displayed significantly higher lung weights compared to WT mice." (PMID 22132068, 2011). "We performed RT-PCRs with TNFα specific primers at 1, 2, 4, 6, 24 and 30 h post infection and observed up regulation of TNFα expression 24 h after infection." (PMID 21655261, 2011). "There were higher concentrations of TNF-α and IL-6 in spleen and more severe hepatic injury in IL-12p40−/− than WT mice after infection." (PMID 22206036, 2011). "Flow cytometry data demonstrated that WNV-induced SK-N-SH cells apoptosis (25.8%) was significantly suppressed in the presence of neutralizing antibodies against IL-1β (12.3%) and TNF-α (13.5%) (p < 0.05) at day 2 after infection." (PMID 21034511, 2010). "The upregulation of TLRs was paralleled by an increase of IL-1β, TNFα, and IFNγ mRNA expression, suggesting the involvement of these cytokines in the defense against infection with C. parapsilosis." (PMID 20454633, 2010). "As expected, infection with GP1V mutant impaired the ability of the donor SP P14-CD8+ thymocytes to produce TNF." (PMID 21124839, 2010).
infection (continued). "The expression profile of three key pro-inflammatory cytokines, namely IFN-γ, IL-6 and TNF-α, was monitored over the course of infection in the serum of animals infected with 107 or 104 PFU of D2Y98P." (PMID 20436920, 2010). "IL-1β and TNFα secretion was measured in the supernatants 12 hours after infection with spores, compared to 6 hour stimulation with HFs." (PMID 20368800, 2010). "But whatever it is, this study reporting 20 cases of TJA infection in patients treated with TNFα blockers is to our knowledge the largest of the literature concerning this peculiar complication." (PMID 20637100, 2010). "We tested cytokine production in the in vitro infections, focusing on TNF-α and IL-10 as the main representatives of the Th-1 and Th-2 responses." (PMID 20500810, 2010). "If TJA infections of large joints are often severe, their incidence appears rare in rheumatic patients exposed to TNFα blockers." (PMID 20637100, 2010). "TNF-α remained inversely correlated with Apo-AI levels after excluding samples with evidence of past infection." (PMID 20098675, 2010). "Surprisingly, this supplementation delayed TNF-α secretion in the infected macrophages at 9 h, which was restored at 24 h post infection." (PMID 20498849, 2010). "It will be of interest to determine if the increased phagosomal ROS during mutant Mtb-infection leads to the oxidation of MKPs, or if other components are involved to modify TNF-α signaling outcome." (PMID 20421951, 2010). "In contrast, there is evidence suggesting a suppressive role for TNF in the generation of T cell responses after infection of mice with LCMV." (PMID 21124839, 2010). "The increase in cell killing correlated with ROS accumulation in the cells as AdMnSOD infection plus BCNU significantly increased ROS levels induced by TNF-α as measured by DCFH oxidation." (PMID 20532186, 2010). "The anti-TNF-α-antibody significantly inhibited macrophage apoptosis induced by MtbΔnuoG infection, as the percentage of apoptotic cells was reduced from 62.3±9.6% to 7.2±1.96% after addition of antibody." (PMID 20421951, 2010). "TNF-α production peaked 3 weeks post-infection and subsequently waned to background levels in both groups." (PMID 20049086, 2010). "Here we show that the apoptogenic phenotype of MtbΔnuoG was significantly reduced in human macrophages treated with caspase-3 and -8 inhibitors, TNF-α-neutralizing antibodies, and also after infection of murine TNF−/− macrophages." (PMID 20421951, 2010). "The mRNA expression of IL-10, INF-γ, and TNF in liver, kidney, and spleen throughout infection was similar in the knockout mice as compared to the wild type mice." (PMID 20403155, 2010). "Ex vivo infection of monocytes and macrophages with the M. tuberculosis strain of the index case showed a significant reduction in the capacity to induce TNF when compared to the laboratory strain H37Rv, related to the attenuated virulence of this strain." (PMID 20652022, 2010). "Infection of macrophages with wild-type Mtb induces a low basal level of TNF-α secretion which is induced by transcriptional upregulation of TNF-α mRNA expression." (PMID 20421951, 2010). "Proinflammatory cytokines IL-1β and TNFα were augmented by the C. parapsilosis-infected oral epithelial cells at early and late infection periods, while IFNγ was involved only at early defense phase, as previously reported with C. albicans." (PMID 20454633, 2010). "TUNEL-positive cells were abundant in WNV-infected cells at day 2 after infection, which reduced significantly (p <0.05) in the presence of anti-IL-1β or -TNF-α." (PMID 21034511, 2010). "Four isolates induced a peak level of TNF-α at day 1 after infection, and this was followed by a rapid decrease in secretion." (PMID 20500810, 2010). "A 3-fold increase in TNF-α secretion in late H5N1/2004 infection was also observed, and these results correlated with the TNF-α mRNA levels." (PMID 21108843, 2010).
infection (continued). "Systemic injection of LPS induces fever and septic shock and is associated with an increase of different cytokines, including TNF-α, IL-1β and IL-6, in the blood circulation and in the brain in a pattern similar to that seen in natural infection." (PMID 21067602, 2010). "Other cytokines that have been found to be important in control of MTb infection include TNF-α, IL-12(p40), IL-18 and IL-17." (PMID 20811496, 2010). "It is known that infection with M. smegmatis induces a potent synthesis and release of TNFα activity, whereas M. avium is a poor inducer." (PMID 20405033, 2010). "Supernatants from infected THP-1 and BMDM cells were collected 3 days post infection and levels of TNF-α were measured by ELISA." (PMID 20421951, 2010). "In summary, at the late phase of infection (i.e. 18 and 24 hours post-infection), TNF-α, IL-6, IL-8, CCL-5/RANTES and CXCL-10/IP-10 mRNA remained at high levels for H5N1/2004 and H9N2/1997; which were in contrast to those observed for H1N1/2002." (PMID 21108843, 2010). "Upon insult or infection, the brain inflammatory response generally involves the production of proinflammatory cytokines such as tumor necrosis factor α (TNFα), interleukins (IL1β, IL-6..)." (PMID 21143912, 2010). "Infection with M. leprae induced high levels of TNF-α production and NF-κB activation in A/J and C57BL/6 macrophages." (PMID 20671924, 2010). "TNFα protein levels increased steadily from day 2 through day 29 post-infection while IL6 and IFNγ protein levels peaked at day 9, before reducing to levels seen in mock infected animals." (PMID 20386712, 2010). "In this study, our data suggests that YopH inhibits the production of IL-1β and TNF-α during the first 24 hours post-infection." (PMID 20565713, 2010). "Memory CD8 T cells have an enhanced capacity to control secondary antigen exposure, through more efficient proliferation, rapid acquisition of effector functions, IFN-γ and TNF-α production, and migration to peripheral sites of infection." (PMID 20161740, 2010). "On the other hand, significant amounts of soluble IL-1β, -6 and TNF-α were detected in supernatant from infected cells at day 2 and 3 after infection (p < 0.05)." (PMID 21034511, 2010). "TNF concentrations rose to a maximum 2-3 weeks after infection and subsequently decreased, in parallel with BCG counts in the spleen and liver." (PMID 20950462, 2010). "We observed that infection with the isolates with the highest intracellular replication levels elicited the lowest TNF-α levels in THP-1-infected cells." (PMID 20500810, 2010). "TNFα is of particular interest as it is important for granuloma formation and the control of infection in Mtb-infected animals and humans." (PMID 20808838, 2010). "Increase in body temperature is a systemic response to infection or inflammation and it is known to be mediated by endogenous pyrogens, including TNFα and IL-6." (PMID 20463923, 2010). "By day 7 of infection, levels of IFNγ (90–250-fold), IL-6 (360–390-fold), IL-17 (30–75-fold), KC (20–35-fold), TNFα (5–13-fold), and IL-2 (2–3.5 fold) were significantly elevated above background in all three vaccinated groups." (PMID 20967278, 2010). "Reduced TNF in the sera of infected Cd36-/- mice around the peak of infection appears to reflect the reduced mycobacterial stimulus rather than acting as a mediator of antimycobacterial defenses." (PMID 20950462, 2010). "History of TJA infection before the introduction of TNFα blockers was reported in three cases, two involving the same joint, versus no control (P = 0.08)." (PMID 20637100, 2010). "On the basis of increased resistance to infection, we predicted enhanced TNF-α secretion in Sphk-1++ infected macrophages over WT infected macrophages." (PMID 20498849, 2010). "Our observation brings new insight into the current knowledge of the risks of infection in patients treated with anti-TNF-α biotherapies." (PMID 20633267, 2010).